CXCL1 (C-X-C motif chemokine ligand 1)
Diseases named in the same sentence as CXCL1 in open-access papers (continued):
Sharing a sentence is not in itself a finding about the gene and the disease.
chronic obstructive pulmonary disease (5 papers, 2016 to 2024). A chronic and progressive lung disorder characterized by the loss of elasticity of the bronchial tree and the air sacs, destruction of the air sacs wall, thickening of the bronchial wall, and mucous accumulation in the bronchial tree. "Moreover, IL-17C exacerbates chronic obstructive pulmonary disease (COPD) through neutrophil recruitment via upregulation of CXCL1." (PMID 38407673, 2024). "An increased plasma level of CXCL1 was exhibited in IPAF compared to idiopathic interstitial pneumonia (IIP), chronic obstructive pulmonary disease (COPD), and healthy controls." (PMID 27958346, 2016).
Cognitive impairment (5 papers, 2021 to 2025). Abnormal cognition is characterized by deficits in thinking, reasoning, or remembering. "Specifically, we observed increased levels of the pro-inflammatory cytokines IL-6, TNF-α, and CXCL1, all of which have been implicated in cognitive impairments associated with AD." (PMID 41282256, 2025). "The MGCs, Mφs, and sera of the PARK2 mouse model displayed decreased expression of parkin and its link to the increased generation of pro-inflammatory cytokines and chemokines (e.g., IFNβ1, TNFα, IL-1β, IL-12, IL-13, IL-17, CCL2, and CXCL1), loss of DA neurons, and cognitive defects in PD." (PMID 34239490, 2021). "Additionally, PARK6-associated PD patients have also shown PINK1 deficiency and its impact on increased generation of pro-inflammatory cytokines and chemokines (e.g., IFNβ1, IL-6, IL-12, IL-13, CCL2, CCL4, and CXCL1), loss of NCs, and the development of cognitive defects." (PMID 34239490, 2021). "In contrast, an identical VX-765 treatment regimen and Casp1 KO in 5- to 8-month-old J20 normalized Iba1+-microglia, elevated hippocampal TNF-α and CXCL1, and reversed or prevented the onset of cognitive impairment." (PMID 36220815, 2022). "On the other hand, microglia in murine models of AD express CXCL1, and the levels of this chemokine in the CSF of AD patients correlate with cognitive impairment, suggesting that CXCL1 is also important in AD." (PMID 33679799, 2021).
cystitis (5 papers, 2015 to 2024). Inflammation of the urinary bladder. "Interestingly, a previous study of a cohort of elderly females and males reported that urinary levels of CXCL1, IL-8, and IL-6 were significantly elevated in patients with acute cystitis compared with patients with asymptomatic bacteriuria (ASB) or negative controls." (PMID 38331474, 2024). "As expected we observed a strong proinflammatory response early in the infection with drastic upregulation of mRNA for inflammatory mediators such as IL-1, CXCL1 and TNF in the bladders of mice experiencing only cystitis or cystitis and pyelonephritis." (PMID 26907352, 2016). "Elevated levels of interleukin-6 (IL-6), keratinocyte cytokine (KC/CXCL1), and granulocyte colony-stimulating factor (G-CSF) in the serum of C57BL/6J mice prior to the second infection predicted the development of chronic cystitis." (PMID 25569799, 2015).
endometrial cancer (5 papers, 2016 to 2023). Primary or metastatic malignant neoplasm involving the endometrium (mucous membrane that lines the endometrial cavity). "Progesterone and calcitriol decrease CXCL1 expression in endometrial cancer cells by decreasing NF-κB activation." (PMID 37108425, 2023). "Progesterone and calcitriol can inhibit ovarian and endometrial cancer cell growth by attenuating the functions of CXCL1; if the expression of CXCL1 is reduced, the inhibitory effect of the two agents is also abrogated." (PMID 32326946, 2020). "CXCL1 is crucial for tumor cell invasiveness in endometrial cancer." (PMID 37108425, 2023). "Moreover, CXCL1 levels in the serum of patients with endometrial cancer are higher than in healthy subjects." (PMID 37108425, 2023).
gastritis (5 papers, 2015 to 2025). Inflammation of the stomach. "This study uncovers the role of METTL3 in regulating CXCL1 expression through m6A modification, thereby activating the NF-κB signaling pathway in the pathogenesis of HP-induced gastritis." (PMID 40825934, 2025). "This study confirms the roles of METTL3 and CXCL1 in HP-induced Gastritis while also elucidating their connection to the NF-κB signaling pathway." (PMID 40825934, 2025). "To explore the function of CXCL1 in HPI gastritis, we conducted GO functional analysis and KEGG pathway analysis on the common differentially expressed genes from the three datasets." (PMID 40825934, 2025). "This study investigates the role of METTL3, an enzyme involved in m6A methylation, in modulating the CXCL1/NF-κB signaling pathway in H. pylori-induced gastritis." (PMID 40825934, 2025). "The analysis suggests that CXCL1 promotes the progression of HPI gastritis by regulating signaling pathways such as the TNF, NF-κB, and chemokine signaling pathway." (PMID 40825934, 2025). "The correlation between METTL3 and CXCL1 suggests a potential therapeutic target for HP-induced gastritis." (PMID 40825934, 2025). "Based on these results, we speculate that the increased expression of CXCL1 may play a role in promoting the progression of HPI gastritis." (PMID 40825934, 2025). "To further demonstrate the role of CXCL1 in promoting HPI gastritis, we divided the gastritis samples from the three datasets into a CXCL1 low-expression (CXCL1-Low) group and a CXCL1 high-expression (CXCL1-High) group based on CXCL1 expression levels, and performed differential analysis." (PMID 40825934, 2025). "Recent studies suggest that METTL3 may play a role in regulating the m6A modification of CXCL1, which is involved in the inflammatory response of Gastritis and subsequently affects the NF-κB signaling pathway." (PMID 40825934, 2025). "Finally, we established a mouse gastritis model using HP bacterial solution gavage to investigate the regulatory role of the METTL3/CXCL1/NF-κB signaling axis in vivo." (PMID 40825934, 2025). "Additionally, high expression of CXCL1 in the Gastritis group was observed in all three HPI gastritis datasets." (PMID 40825934, 2025). "Finally, we investigated whether HP exacerbates the inflammatory response in gastritis mice through the METTL3/CXCL1/NF-κB signaling axis." (PMID 40825934, 2025). "In conclusion, METTL3 upregulates CXCL1 expression through m6A modification, activating the NF-κB signaling pathway and exacerbating the inflammatory response in HPI-induced gastritis in mice." (PMID 40825934, 2025).
Hyperglycemia (5 papers, 2021 to 2024). An increased concentration of glucose in the blood. "Our data support the concept that hyperglycemia strongly increases the expression of CXCR2 and its ligand CXCL1/KC." (PMID 34571976, 2021). "GcgR antagonist restored neutrophil migration, reduced CFU numbers in the peritoneal cavity and improved survival rate of diabetic mice after CLP procedure, however, the treatment did no alter hyperglycemia, CXCL1/KC plasma levels and blood neutrophilia." (PMID 34295325, 2021).
meningitis (5 papers, 2018 to 2022). A disorder characterized by acute inflammation of the meninges of the brain and/or spinal cord. "CXCL1 recruits and activates neutrophils, is associated with protection in H. pylori and meningitis infections and is involved in the signaling pathways of G protein-coupled receptors." (PMID 35562916, 2022).
metabolic syndrome (5 papers, 2019 to 2026). A cluster of metabolic risk factors for CARDIOVASCULAR DISEASES and TYPE 2 DIABETES MELLITUS. "The translational relevance of these findings was supported by the association that we found between blood neutrophils count and Cxcl1 plasma levels with markers of fatty liver and visceral adiposity in subjects with metabolic syndrome." (PMID 38327649, 2023). "Altered levels of distinct chemokines, like CCL5/RANTES, CXCL12/SDF-1a, CCL7/MCP-3, CCL2/MCP-1, CXCL1/GROa, and the eotaxin family, contribute to the development and/or exacerbation of inflammation, which is a common feature of numerous skin diseases as well as metabolic syndrome." (PMID 42042898, 2026).
myocardial infarction (5 papers, 2021 to 2024). Gross necrosis of the myocardium, as a result of interruption of the blood supply to the area, as in coronary thrombosis. "However, changes in CXCL1, MCP-1, and CXCL6 expression may be related to other mechanisms in the process of myocardial infarction, which requires further research effort." (PMID 38124195, 2023).
myocarditis (5 papers, 2014 to 2025). Myocarditis is a condition that is characterized by inflammation of the heart muscle (myocardium). "To directly test whether CXCL1/KC caused the amelioration of myocarditis, we treated mice, after challenge with heart-specific self peptide, with exogenous recombinant CXCL1/KC." (PMID 24586934, 2014). "It has been suggested that the level of CXCL1 was in keep with the extent of myocardial inflammation and the percentage of CD14++DN16− monocytes." (PMID 34781940, 2021). "More important, our finding that one defined chemokine, CXCL1/KC, abrogates autoimmune inflammatory heart disease opens the possibility for a new specific treatment for myocarditis and cardiomyopathy." (PMID 24586934, 2014). "Indeed, inhibiting TLR4 might be contraindicated in myocarditis due to its essential function in inducing increased CXCL1/KC protein expression in the course of myocarditis." (PMID 24586934, 2014). "To test this hypothesis, we administered CXCL1/KC to BALB/c wild type mice after immunization with M7Aα peptide in CFA; i.e., after the immune response has been induced experimentally but before myocarditis was apparent." (PMID 24586934, 2014).
nonalcoholic steatohepatitis (5 papers, 2013 to 2023). "In HCV, HBV, alcohol-related hepatitis and nonalcoholic steatohepatitis, CXCL1 expression in the liver background closely reflected the hepatocyte damage level and increased portal vein pressure by promoting sinusoid microthrombi." (PMID 37037815, 2023). "For instance, a previous study has shown that an excess concentration of hepatic CXCL1 leads to an oxidative stress response, as indicated by the increased activation of stress kinases such as apoptosis signal-regulating kinase 1, which accelerates the nonalcoholic steatohepatitis progression." (PMID 37229425, 2023).
pancreatitis (5 papers, 2012 to 2025). Inflammation of the pancreas. "Elevated levels of serum cytokines and chemokines including IL-6, CCL2, and CXCL1 have been reported to be pathological hallmarks of pancreatitis after CVB3 infection." (PMID 27195463, 2016). "However, levels of the neutrophil chemoattractant CXCL1 increased approximately 2-fold in both the pancreas and lungs 9 h after pancreatitis induction as compared to controls peaked at 24 h and then declined." (PMID 23110041, 2012).
parasitemia (5 papers, 2015 to 2025). "Both of these cytokines, as well as IFN-γ, were indirectly correlated with parasitemia through MCs, GM-CSF, KC/CXCL1 and IL-17 at the same time point." (PMID 35154114, 2022).
plaque psoriasis (5 papers, 2021 to 2024). "In addition, the IL-17A antagonist (secukinumab) used to treat moderate to severe plaque psoriasis can significantly inhibit the secretion of CXCL1 and CXCL8 by keratinocytes, and almost completely eliminate the infiltration of neutrophils in skin lesions." (PMID 33613635, 2021). "Higher expression of neutrophil chemokines, including CXCL1, CXCL2, and CXCL8, were observed in GPP patients compared with plaque psoriasis patients." (PMID 38378928, 2024). "In this observational study using transdermal analysis patch (TAP), levels of skin surface IL-1α, hBD-1, hBD-2, CXCL-1/2, and CXCL-8 of psoriasis vulgaris (PV) patients over biological therapy were assessed." (PMID 38003437, 2023).
prostatitis (5 papers, 2018 to 2023). An infectious or non-infectious inflammatory process affecting the prostate gland. "We next tested whether blocking CXCL1 signaling could attenuate the mechanical hypersensitivity caused by prostatitis." (PMID 31653262, 2019). "CXCL1 increases osteoclast maturation, which leads to bone remodeling and the forming of prostate metastasis." (PMID 37108425, 2023). "In this study, we found that a novel mechanism of activated spinal astrocytes plays a crucial role in maintaining chronic prostatitis-induced persistent pain via connexin-43-regulated CXCL1 production and secretion." (PMID 31653262, 2019). "Another interesting finding is that the upregulation of Cx43 contributes to prostatitis-induced persistent pain by enhancing the chemokine CXCL1 production and release." (PMID 31653262, 2019). "In this study, we have demonstrated that activated spinal astrocytes play a crucial role in maintaining chronic prostatitis-induced persistent pain via Cx43-regulated CXCL1 production and secretion." (PMID 31653262, 2019). "Our results demonstrate that activated astrocytes contribute to the later phase of carrageenan-induced prostatitis pain via Cx43-regulated CXCL1 production and secretion." (PMID 31653262, 2019). "The present study showed that prostatitis induced a profound and persistent upregulation of Cx43 in spinal astrocytes, and intrathecal injection of CBX effectively reduced prostatitis pain and the content of CXCL1 in CSF." (PMID 31653262, 2019). "CXCL1, on the other hand, acts on osteoclast precursors, which leads to the differentiation of these cells into osteoclasts and thus to bone remodeling, which enhances prostate metastasis." (PMID 37108425, 2023). "To investigate the effect of CBX on the secretion of CXCL1 in a mouse model of carrageenan-induced prostatitis, we compared CXCL1 levels in cerebrospinal fluid (CSF) in the saline-injected group, the PBS-treated carrageenan injection group, and the CBX-treated carrageenan injection group." (PMID 31653262, 2019). "Furthermore, the synthesis and secretion of the chemokine CXCL1, a mediator of neuroinflammation, in the spinal dorsal horn is increased in the prostatitis model." (PMID 31653262, 2019). "To demonstrate whether a similar molecular mechanism exists in prostatitis pain, we first examined the expression of CXCL1 in the spinal cord dorsal horn 5 weeks after carrageenan injection." (PMID 31653262, 2019). "Several genes previously associated with prostate disease were also identified as affected in the current study: Fli1 (stromal DMR), Egf (epithelial DMR), Dgk2 (stromal differentially expressed mRNA), Snai2 and Cxcl1 (epithelial differentially expressed mRNA)." (PMID 30778168, 2019). "It was reported that electroacupuncture could release pain symptoms of chronic prostatitis rats while inhibiting astrocyte activation and CXCL1 expressions in astrocytes in the L5-S2 spinal dorsal horn, indicating that CXCL1 in astrocytes might be a potential target for chronic prostatitis." (PMID 38023826, 2023). "Moreover, CXCL1 and CXCL2 were enhanced in Gr(+)-sorted neutrophils infiltrating the gland in the LPS-induced prostatitis model as well as in LPS-elicited peritoneal cells from animals treated with testosterone." (PMID 30233581, 2018).
Salmonella Infections (5 papers, 2011 to 2025). Infections with bacteria of the genus SALMONELLA. "(C–E) RT-qPCR analysis of mRNAs encoding inflammatory cytokines (Tnfα, Il1β, and Il6), chemokines (Ccr2, Ccl2, Cxcl1, and Cxcl10) and macrophage biomarkers (Nos2 and Arg1) in BMDMs measured at the indicated times after Salmonella infection (multiplicity of infection [MOI] = 1) (n = 5)." (PMID 39475776, 2024).
squamous cell carcinoma (5 papers, 2008 to 2025). A carcinoma arising from squamous epithelial cells. "In support of this, EGF was found to activate NF-κB and induce CXCL1 in murine squamous cell carcinoma." (PMID 23800251, 2013). "It was demonstrated that the tumor samples of squamous cell carcinoma (SCC) contained high levels of IL‐6, IL‐8, and CXCL1 gene transcripts, a trait that was transferred to normal fibroblasts upon their co‐culture with FaDu carcinoma cells, suggesting paracrine signaling between these cells." (PMID 40621923, 2025).
type 1 diabetes (5 papers, 2017 to 2024). "In the treated type 1 diabetes mouse model, serum TNF-α, IL-12, and IFN-γ secretion were greatly reduced in the OI group, whereas CXCL1 and IL-10 production was restored." (PMID 36918798, 2023). "The patients with type-1 diabetes (T1D) or T2D were found to have elevated serum levels of CXCL1 as compared with non-diabetic controls." (PMID 28396851, 2017).
Airway obstruction (4 papers, 2010 to 2024). Obstruction of conducting airways of the lung. "RSV RNA loads were detected in peripheral blood from day 1 to 14 post-inoculation, peaked on day 5 and significantly correlated with nasal and lung RSV loads, airway obstruction, and blood CCL2 and CXCL1 expression." (PMID 20843364, 2010).
alcoholic hepatitis (4 papers, 2013 to 2021). Acute hepatitis resulting from ingestion of alcohol. "Ccl20 and Cxcl1 mediate LPS-induced liver injury and are potential drivers of inflammation and fibrosis in alcoholic hepatitis." (PMID 34684425, 2021). "Hepatic CXCL1 mRNA levels correlated positively with liver PMN infiltration in the alcoholic hepatitis period." (PMID 28320485, 2017). "Furthermore, a correlation was found between CXCL1 protein concentration and neutrophil count in the liver of patients with alcoholic hepatitis." (PMID 23875831, 2013).
amebiasis (4 papers, 2020 to 2025). A parasitic infectious disorder caused by amoebas. "In a prior investigation by our group, increased levels of CXCL1 were observed in classical monocytes from male mice, both under steady-state conditions and on day 3 of hepatic amebiasis, which led to an increased immunopathology caused by the recruitment of further immune cells." (PMID 40794782, 2025). "Interestingly, expression of TNF and CXCL1 was higher in monocytes from male individuals than in those from females; this applied to both Ly6Chi monocytes in the murine model of amebiasis and CXCL1 in LPS-stimulated CD14++CD16- monocytes from healthy human subjects." (PMID 33829283, 2021).
Aortic dissection (4 papers, 2019 to 2021). Aortic dissection refers to a tear in the intimal layer of the aorta causing a separation between the intima and the medial layers of the aorta. "Additionally, neutrophil infiltration derived by a C-X-C motif chemokine ligand 1 (CXCL1) has also been reported to induce progression from aortic dissection to aortic rupture in mice fed with BAPN and infused with Ang-II." (PMID 33925479, 2021). "In addition to CXCL1 and G-CSF, multiple other cytokines and chemokines, including IL-6 and MCP-1, have been reported to play a role in the local and systemic inflammatory responses after acute aortic dissection." (PMID 32027731, 2020).
atopic dermatitis (4 papers, 2011 to 2025). "To further study the role of IL-17 (Th17 cytokine) in high sensitivity of Pglyrp3−/− mice to oxazolone-induced atopic dermatitis, we determined the protein levels of an IL-17-induced chemokine, CXCL-1, in the ears of WT and Pglyrp3−/− mice." (PMID 21949809, 2011). "Atopic dermatitis (AD) can increase the level of CXCL1 by activating type 2 IL-4R." (PMID 40005151, 2025). "In addition, IL-4R signaling could increase the CXCL1 level in a mouse model of atopic dermatitis." (PMID 40005151, 2025).